MFRP (membrane frizzled-related protein)
Diseases named in the same sentence as MFRP in open-access papers (continued):
Sharing a sentence is not in itself a finding about the gene and the disease.
retinitis pigmentosa (12 papers, 2009 to 2025). Retinitis pigmentosa (RP) is an inherited retinal dystrophy leading to progressive loss of the photoreceptors and retinal pigment epithelium and resulting in blindness usually after several decades. "We reported autosomal recessive posterior microphthalmia, atypical retinitis pigmentosa, and retinoschisis caused by a novel mutation in the MFRP gene in this consanguineous marriage family." (PMID 35402469, 2022). "Importantly, much like the recent ADIPOR1 reports, MFRP mutations are also known to cause retinitis pigmentosa in human patients and it will be instrumental to assess whether their disease is caused by ADIPOR1 loss and whether it can be prevented via rescue of ADIPOR1 expression." (PMID 30254279, 2018). "Here, we present the clinical and genetic data of a patient in which a phenotypic association of posterior microphthalmos, non-pigmented retinitis pigmentosa, retinoschisis, and optic nerve drusen was caused by a novel variant in membrane frizzled-related protein (MFRP)." (PMID 35402469, 2022). "Mutations in the membrane frizzled-related protein (MFRP/Mfrp) gene, specifically expressed in the retinal pigment epithelium (RPE) and ciliary body, cause nanophthalmia or posterior microphthalmia with retinitis pigmentosa in humans, and photoreceptor degeneration in mice." (PMID 25357075, 2014).
autosomal recessive nanophthalmos (6 papers, 2009 to 2020). "MFRP gene mutations had been previously found also in association with another ocular phenotype, consisting of a form of autosomal-recessive nanophthalmos with shallow anterior chamber and high corneal curvature, but without clear-cut evidence of retinitis pigmentosa." (PMID 23112574, 2012). "MFRP is expressed as a dicistronic transcript with C1QTNF5 and is mutated in human autosomal recessive nanophthalmos and also in the mouse, in the Mfrp rd6 mutant, which is associated with retinal degeneration." (PMID 22110650, 2011). "MFRP mutations had been previously related to a different ocular phenotype, characterized by autosomal-recessive nanophthalmos without fundoscopic or electrophysiologic signs of retinal dystrophy." (PMID 23112574, 2012). "Nanophthalmos type 2 (NNO2; #609549) and isolated microphthalmia type 6 (MCOP6; OMIM #613517) are autosomal recessive conditions associated with pathogenic variants in the membrane frizzled-related protein (MFRP) and serine protease 56 (PRSS56) genes, respectively." (PMID 32454992, 2020).
angle-closure glaucoma (4 papers, 2008 to 2025). The sudden increase of intraocular pressure, resulting in pain and an abrupt decrease in visual acuity. "MFRP deficiency causes abnormal eye growth along the visual axis and significant visual comorbidities, such as angle closure glaucoma, cystic macular edema, and exudative retinal detachment." (PMID 29170418, 2017). "The purpose of our study was to investigate whether there are significant associations between angle-closure glaucoma and sequence variants in the MFRP gene reported previously in Taiwanese subjects." (PMID 18781223, 2008).
myopia (4 papers, 2008 to 2025). "Using a complementary genetic approach, we show that besides promoting ocular growth during normal development, PRSS56 and MFRP are also required for pathological ocular elongation observed in a mouse model of severe and early-onset myopia caused by a null mutation in Irbp." (PMID 33755662, 2021). "Using a complementary genetic approach, we show that loss of PRSS56 or MFRP function prevents excessive ocular axial growth in a mouse model of early-onset myopia caused by a null mutation in Irbp, thus, demonstrating that PRSS56 and MFRP are also required for pathological ocular elongation." (PMID 33755662, 2021). "However, genetic variants of PRSS56 and MFRP are also associated with common forms of myopia, raising the possibility that these factors may also play a role during emmetropization." (PMID 33755662, 2021). "Moreover, we demonstrate that loss of PRSS56 or MFRP function prevents excessive ocular axial elongation in a mouse model of early-onset myopia caused by a null mutation in Irbp, further establishing PRSS56 and MFRP as critical regulators of ocular growth." (PMID 33755662, 2021).
autosomal recessive retinitis pigmentosa (3 papers, 2012 to 2021). Autosomal recessive retinitis pigmentosa (RP) is an autosomally recessive inherited retinal dystrophy leading to progressive loss of the photoreceptors and retinal pigment epithelium and resulting in blindness usually after several decades. "The rd6 mouse is a biologic model of retinal pigment epithelium-based autosomal recessive retinitis pigmentosa caused by the mutation in the MFRP (membrane-type frizzled related protein) gene." (PMID 30759764, 2019).
Optic disc drusen (3 papers, 2012 to 2024). Optic disc drusen are acellular, calcified deposits within the optic nerve head. "However, since 2006, a series of cases have been reported MFRP mutations are associated with posterior nanophthalmos, RP, macular abnormalities, and optic disc drusen." (PMID 39076172, 2024).
acute angle-closure glaucoma (2 papers, 2008 to 2024). "In conclusion, sequence variants of MFRP do not appear to be associated with a risk for acute angle-closure glaucoma." (PMID 18781223, 2008).
autism (1 paper, 2024). Persistent deficits in social interaction and communication and interaction as well as a markedly restricted repertoire of activity and interest as well as repetitive patterns of behavior. "Regulatory inference using the Genie3 algorithm identified direct regulation of IGF1 by SIK1, MFRP, CHD7, NIPBL, EXOC5, and ARID2, with SIK1 and SPARCL1 significantly downregulated in autism brain organoids, potentially affecting IGF1 expression." (PMID 39376742, 2024).
nanophthalmia (1 paper, 2014). Nanophthalmia is a severe form of microphthalmia characterized by a small eye with a short axial length, severe hyperopia, an elevated lens/eye ratio, and a high incidence of angle-closure glaucoma. "MFRP mutations in humans are associated with nanophthalmia or posterior microphthalmia with autosomal recessive retinitis pigmentosa (RP), characterized by retinal spots, foveoschisis and optic nerve head drusen." (PMID 25357075, 2014). "Finally, human mutations in MFRP have been associated with nanophthalmia or posterior microphthalmia with shortening of the posterior segment of the eye, an expected consequence of reduced retinal and RPE development." (PMID 25357075, 2014).
refractive error (1 paper, 2025). A defect in the focusing of light on the retina as in astigmatism, myopia, or hyperopia. "Some genes implicated in IRDs (e.g., BEST1, LRP5, MFRP) affect organogenesis, modulating ocular development in the foetal and early childhood phases, leading to early-onset myopic or hyperopic refractive errors." (PMID 41465105, 2025).
Rod-cone dystrophy (1 paper, 2010). An inherited retinal disease subtype in which the rod photoreceptors appear to be more severely affected than the cone photoreceptors. "To conclude, we have expanded and refined the phenotypic description of patients with the rod-cone dystrophy associated with mutations in the MFRP gene." (PMID 20361016, 2010).
tumor (1 paper, 2024). "Uc.110 activated the WNT pathway by upregulating the expression of membrane frizzled-related protein (MFRP), by sponging the tumor suppressor microRNA miR-544." (PMID 38699302, 2024).
MFRP also shares sentences with these, for which no sentence is quoted: Retinal dystrophy (4 papers); primary angle-closure glaucoma (3); Anophthalmia (2); retinal detachment (2); Stargardt disease (2); Atrophy (1); cancer (1); congenital cataract (1); cystoid macular edema (1); Hypermetropia (1); macular abnormalities (1); macular cysts (1); macular edema (1); myeloid leukemia (1); nail-patella syndrome (1); night blindness (1); Retinal atrophy (1); retinal disease (1); retinal vein occlusion (1); retinitis punctata albescens (1); retinoschisis (1); vision disorder (1).